SKP1 (S-phase kinase associated protein 1)
Description:
Essential component of the SCF (SKP1-CUL1-F-box protein) ubiquitin ligase complex, which mediates the ubiquitination of proteins involved in cell cycle progression, signal transduction and transcription. In the SCF complex, serves as an adapter that links the F-box protein to CUL1. The functional specificity of the SCF complex depends on the F-box protein as substrate recognition component. SCF(BTRC) and SCF(FBXW11) direct ubiquitination of CTNNB1 and participate in Wnt signaling. SCF(FBXW11) directs ubiquitination of phosphorylated NFKBIA. SCF(BTRC) directs ubiquitination of NFKBIB, NFKBIE, ATF4, SMAD3, SMAD4, CDC25A, FBXO5, CEP68 and probably NFKB2. SCF(SKP2) directs ubiquitination of phosphorylated CDKN1B/p27kip and is involved in regulation of G1/S transition. SCF(SKP2) directs ubiquitination of ORC1, CDT1, RBL2, ELF4, CDKN1A, RAG2, FOXO1A, and probably MYC and TAL1. SCF(FBXW7) directs ubiquitination of cyclin E, NOTCH1 released notch intracellular domain (NICD), and probably PSEN1. SCF(FBXW2) directs ubiquitination of GCM1. SCF(FBXO32) directs ubiquitination of MYOD1. SCF(FBXO7) directs ubiquitination of BIRC2 and DLGAP5. SCF(FBXO33) directs ubiquitination of YBX1. SCF(BTRC) mediates the ubiquitination of NFKBIA at 'Lys-21' and 'Lys-22'; the degradation frees the associated NFKB1-RELA dimer to translocate into the nucleus and to activate transcription. SCF(CCNF) directs ubiquitination of CCP110. SCF(FBXL3) and SCF(FBXL21) direct ubiquitination of CRY1 and CRY2. SCF(FBXO9) directs ubiquitination of TTI1 and TELO2. SCF(FBXO10) directs ubiquitination of BCL2. Core component of the Cul7-RING(FBXW8) ubiquitin ligase complex, which mediates the ubiquitination and subsequent proteasomal degradation of target proteins. Also acts as a core component of the Cul1-RING(FBXL4) ubiquitin ligase complex, which mediates the ubiquitination and subsequent proteasomal degradation of BNIP3 and BNI3L.
Synonyms: p19A; OCP-II; EMC19; OCP2; SKP1A; TCEB1L; MGC34403
Tractability: Small molecule: a structure with a bound ligand is known. PROTAC: UniProt records ubiquitination sites on it; ubiquitination databases record sites on it; its protein half-life has been measured.
Gene: Protein-coding gene on chromosome 5 (134,148,935 to 134,177,029, reverse strand). Ensembl gene ENSG00000113558.
Subcellular location (Human Protein Atlas): Cytosol; Nucleoplasm; Basal body; Centrosome; Cytokinetic bridge; Primary cilium
Pathways (Reactome):
Immune System: Activation of NF-kappaB in B cells; Antigen processing: Ubiquitination & Proteasome degradation; CLEC7A (Dectin-1) signaling; Dectin-1 mediated noncanonical NF-kB signaling; Downstream TCR signaling; FCERI mediated NF-kB activation; GSK3B-mediated proteasomal degradation of PD-L1(CD274); Interleukin-1 signaling; MAP3K8 (TPL2)-dependent MAPK1/3 activation; NIK-->noncanonical NF-kB signaling; Prolactin receptor signaling
Cell Cycle: Cyclin D associated events in G1; FBXL7 down-regulates AURKA during mitotic entry and in early mitosis; Regulation of PLK1 Activity at G2/M Transition; SCF(Skp2)-mediated degradation of p27/p21; SCF-beta-TrCP mediated degradation of Emi1; Ubiquitin-Mediated Degradation of Phosphorylated Cdc25A
Signal Transduction: Degradation of GLI1 by the proteasome; Degradation of GLI2 by the proteasome; Degradation of beta-catenin by the destruction complex; GLI3 is processed to GLI3R by the proteasome; NOTCH1 Intracellular Domain Regulates Transcription; Negative regulation of NOTCH4 signaling
Disease: Constitutive Signaling by NOTCH1 HD+PEST Domain Mutants; Constitutive Signaling by NOTCH1 PEST Domain Mutants; Loss of Function of FBXW7 in Cancer and NOTCH1 Signaling; Nuclear events stimulated by ALK signaling in cancer; Vpu mediated degradation of CD4
Cellular responses to stimuli: GSK3B and BTRC:CUL1-mediated-degradation of NFE2L2; Regulation of BACH1 activity
Circadian clock: Degradation of CRY and PER proteins
DNA Replication: Orc1 removal from chromatin
Gene expression (Transcription): Regulation of RUNX2 expression and activity
Metabolism of proteins: Neddylation
Transport of small molecules: Iron uptake and transport
Gene Ontology:
Molecular function: beta-catenin binding; cullin family protein binding; F-box domain binding; molecular function activator activity; protein binding; protein domain specific binding; ubiquitin ligase activator activity; ubiquitin ligase complex scaffold activity; ubiquitin-like ligase-substrate adaptor activity
Biological process: chromatin remodeling; maintenance of protein location in nucleus; proteasome-mediated ubiquitin-dependent protein catabolic process; protein K48-linked ubiquitination; protein polyubiquitination; protein ubiquitination; SCF-dependent proteasomal ubiquitin-dependent protein catabolic process; centrosome duplication; cilium assembly; G1/S transition of mitotic cell cycle; heterochromatin formation; intracellular iron ion homeostasis; limb development; negative regulation of DNA-templated transcription; neural crest cell differentiation; regulation of apoptotic process; regulation of BMP signaling pathway; regulation of cell cycle; regulation of cell cycle process; regulation of centrosome duplication; regulation of circadian rhythm; regulation of DNA damage checkpoint; regulation of DNA-templated transcription; regulation of inflammatory response; regulation of mitophagy; and 5 more
Cellular component: Cul7-RING ubiquitin ligase complex; cytoplasm; nucleus; PcG protein complex; SCF ubiquitin ligase complex; centrosome; chromatin; cytosol; nucleoplasm; PRC1 complex; ubiquitin ligase complex
Genetic constraint (gnomAD): Loss-of-function variants: 0 observed, 9.23 expected, observed/expected ratio (o/e) 0, 90% interval 0 to 0.32. That is too few expected variants to judge how well the gene tolerates losing a copy. Missense variants: 25 observed, 90.42 expected, observed/expected ratio (o/e) 0.28, 90% interval 0.2 to 0.39. Synonymous variants: 26 observed, 27.75 expected, observed/expected ratio (o/e) 0.94, 90% interval 0.69 to 1.3.
Homologues: Orthologues: chimpanzee SKP1 (100% identical), dog SKP1 (100% identical), pig SKP1 (100% identical), tropical clawed frog skp1 (100% identical), mouse Skp1 (99% identical), rat Skp1 (99% identical), zebrafish skp1 (99% identical), guinea pig Skp1 (94% identical), Drosophila melanogaster SkpA (77% identical), Caenorhabditis elegans skr-1 (71% identical), Drosophila melanogaster SkpB (69% identical), Caenorhabditis elegans skr-2 (61% identical), and 20 more.
Diseases named in the same sentence as SKP1 in open-access papers:
SKP1 is named in the same sentence as 59 diseases in open-access papers, as found by Europe PMC text mining. Sharing a sentence is not in itself a finding about the gene and the disease. The quoted sentences say what the papers report.
viral infection (9 papers, 2012 to 2023). "(2016) found that cotton leaf curl Multan betasatellite (CLCuMuB) βC1 can interact with tobacco S-phase kinase associated protein 1 (SKP1) to subvert plant ubiquitination, thus promoting virus infection and disease symptom induction." (PMID 32973859, 2020). "We also observed that genes involved in plant immunity, such as Hsp90 (heat shock protein 90) and its co-chaperone Sgt1 (suppressor of the G2 allele of Skp1), may contribute to the basal resistance to viral infection." (PMID 38140611, 2023). "Furthermore, the cotton leaf curl Multan betasatellite (CLCuMuB) βC1 protein disrupts the integrity of the SCF complex by binding to SKP1, resulting in suppressed jasmonate signaling to help the viral infection." (PMID 37628763, 2023). "Furthermore, interactions between the beet western yellow virus (BWYV) P0 protein and SKP1 modulates programmed cell death during virus infection." (PMID 24653727, 2014). "In addition, CLCuMuB βC1 protein can disrupt the integrity of the SKP1/Cullin1 (CUL1)/F-box (SCF) complex SCFCOI1 by interacting with s-phase kinase-associated protein 1 (SKP1), thereby disrupting plant ubiquitination and promoting viral infection and symptom induction." (PMID 36851725, 2023). "Similarly, tomato chlorosis virus (ToCV) P22 protein interacts with SKP1 and hampers the assembly of the SCF complex, leading to suppressed auxin signaling and facilitating viral infection." (PMID 37628763, 2023). "PVX is also known to interact with SKP1 but the role of this cofactor in virus infection is not yet clarified." (PMID 24653727, 2014). "Here we report that F-box only protein Fbxo21, a functionally unknown component of SCF (Skp1–Cul1–F-box protein) complex, facilitates Lys29-linkage and activation of ASK1 (apoptosis signal-regulating kinase 1), and promotes type I interferon production upon viral infection." (PMID 27063938, 2016).
breast carcinoma (8 papers, 2014 to 2025). "However, almost all interactions of CDK1 and those of SKP1 with CDK1 neighboring proteins were breast cancer-exclusive." (PMID 33670716, 2021). "Although it was composed of target proteins shared by the MCF7 and DG75 cell datasets, the CDK1/SKP1 proximal network had mostly interactions that were exclusive to the breast cancer or DG75 cell network, suggesting that its regulation by SYK could be different depending on the cell type." (PMID 33670716, 2021). "Almost all SKP1 and CDK1 interactors were present in the breast cancer and Burkitt lymphoma networks." (PMID 33670716, 2021).
hepatocellular carcinoma (6 papers, 2016 to 2025). A malignant tumor that arises from hepatocytes. "CCDC183-AS1 enhances hepatocellular carcinoma progression by regulating SKP1 expression via MIR-589-5P." (PMID 35087586, 2022). "CAND1 regulates the reprogramming of lipid metabolism through SKP1-Cullin-1-F-box (SCF,E3 ligase)-mediated heterogeneous nuclear ribonucleoprotein A2/B1 ubiquitination, promoting hepatocellular carcinoma." (PMID 39944823, 2025). "The TCGA database showed that FBXL6, an Skp1-Cullin-F box (SCF) E3 ligase, is highly expressed in most human cancers, including liver hepatocellular carcinoma (LIHC), namely, HCC (P < 0.001)." (PMID 38124228, 2023).
Parkinson disease (5 papers, 2016 to 2024). A progressive degenerative disorder of the central nervous system characterized by loss of dopamine producing neurons in the substantia nigra and the presence of Lewy bodies in the substantia nigra and locus coeruleus. "In agreement with our findings in humans and MPTP-induced parkinsonism, cultured naïve SN4741 DA neurons exposed to the DA neuron selective neurotoxin MPP+, a dynamic producer of ROS, caused an early and progressive down-regulation of Skp1, concomitantly with Aldh1 and Hsc-70 proteins." (PMID 37644186, 2024).
bladder cancer (3 papers, 2016 to 2022). "After the expression level of SKP1 increased, the proliferative activity was significantly promoted, indicating that SKP1 can enhance the proliferative activity of bladder cancer and reverse cell proliferation inhibition caused by circGLIS3 shRNA." (PMID 33656636, 2022). "SKP1 has been reported to be associated with the progression of bladder cancer." (PMID 33656636, 2022). "Stable knockdown of miR-1273f expression can effectively inhibit G0/G1 phase arrest caused by knocking down circGLIS3 and promote the proliferation of bladder cancer cells and promote the expression of SKP1 and cyclin D1." (PMID 33656636, 2022). "Mechanically, circGLIS3 upregulates the expression of SKP1 by adsorbing miR-1273f and then promotes the expression of cyclin D1, ultimately promoting bladder cancer cell proliferation." (PMID 33656636, 2022). "Increased SKP1 expression would further promote the expression of cyclin D1, ultimately leading to an abnormally excessive proliferation of bladder cancer cells." (PMID 33656636, 2022). "Mechanically, circGLIS3 upregulates the expression of SKP1 by adsorbing miR-1273f and then promotes cyclin D1 expression, ultimately promoting the proliferation of bladder cancer cells." (PMID 33656636, 2022). "In this study, we ascertained that the SKP1 level of protein expression in bladder cancer cells increased significantly." (PMID 33656636, 2022). "SKP1 was demonstrated to be involved in an axis to promote bladder cancer proliferation and is controlled by circGLIS3." (PMID 34195188, 2021). "Further mechanistic experimental studies have indicated that circGLIS3 may competitively bind miR-1273f and promote SKP1 expression, thereby promoting cyclin D1 overexpression, ultimately promoting the proliferation of bladder cancer cells." (PMID 33656636, 2022). "Compared with SV-HUC-1, SKP1 expression was increased in UM-UC-3 and T24, suggesting that SKP1 may participate in the development of bladder cancer." (PMID 33656636, 2022). "However, there have been few reports to date on SKP1’s effect on bladder cancer." (PMID 33656636, 2022). "To further determine whether the SKP1 pathway promotes the proliferation of bladder cancer cells consistent with circGLIS3-Cyclin D1, we transiently overexpressed SKP1 in circGLIS3 shRNA stable cell lines and used flow cytometry to detect the cycle change of bladder cancer cells." (PMID 33656636, 2022). "The predicted results suggested that circGLIS3 may adsorb miR-1273f like a sponge, so that the binding of miR-1273f to SKP1 decreases, thereby promoting the expression of SKP1 and increasing the expression of Cyclin D1, and ultimately promoting the proliferation of bladder cancer cells." (PMID 33656636, 2022). "To verify this, we first used Western blot to detect SKP1 expression in normal bladder epithelial cells (SV-HUC-1) and bladder cancer cells (UM-UC-3 and T24)." (PMID 33656636, 2022).
colon cancer (3 papers, 2020 to 2025). "As expected, high expression of SKP1 is associated with poor prognosis of colon cancer patients." (PMID 33292299, 2020). "In colon cancer, CACYBP enhances proliferation by interacting with Skp1 to degrade p27ˆKip1, while in cholangiocarcinoma, it promotes progression by inhibiting MCM2 ubiquitination and activating the Wnt/β-catenin signaling pathway." (PMID 40167359, 2025). "SKP1 was upregulated in CRC-SCs and predicted poor prognosis of colon cancer patients." (PMID 33292299, 2020).
gastric cancer (3 papers, 2019 to 2025). A primary or metastatic malignant neoplasm involving the stomach. "In gastric cancer, some studies suggest it promotes proliferation by binding Skp1, degrading p27ˆKip1, and increasing Cyclin E." (PMID 40167359, 2025). "Skp1 and SCF assembly components are coexpressed during the development of breast, colon, prostate, lung and gastric cancers." (PMID 33329729, 2020). "Despite its known function as a component of the Skp1-Cullin-F-box (SCF) ubiquitin ligase complex, the role of FBXW5 in gastric cancer tumorigenesis and metastasis has not been investigated." (PMID 31213005, 2019).
lung carcinoma (3 papers, 2015 to 2021). "Here we showed that Skp1 was overexpressed in lung cancers and was inversely associated with clinical outcome, while knockdown of Skp1 resulted in inhibition of cancer cell proliferation and clonogenic activity." (PMID 26474281, 2015). "Although SKP1 alterations occur most frequently in uterine and lung cancers, most substitutions only occur in a single cancer type, except for E133K/Q (bladder, breast)." (PMID 35008511, 2021). "A previous study demonstrated that Skp2 is a target of STAT3, and our previous work showed that Skp2 is dissociated from Skp1 and underwent proteolysis in lung cancer cells treated with 6-OAP." (PMID 27835873, 2017). "6-OAP showed potent in vitro and in vivo anti-lung cancer activity with minimal adverse effect, demonstrating the therapeutic potentials of Skp1 inhibitors." (PMID 26474281, 2015). "Targeting of Skp1 by a small compound 6-O-angeloylplenolin (6-OAP) results in dissociation and degradation of Skp2 and mitotic arrest of lung cancer cells." (PMID 27835873, 2017). "Given that 6-OAP is a Skp1 inhibitor, our data suggest that this compound may target Skp1 and STAT3 to suppress Skp2, augmenting its anti-lung cancer activity." (PMID 27835873, 2017). "Therefore, 6-OAP inhibited both Skp1 and STAT3 to repress Skp2, exhibiting inhibitory effects on lung cancer cell proliferation and survival." (PMID 27835873, 2017).
non-small cell lung carcinoma (3 papers, 2015 to 2025). A group of at least three distinct histological types of lung cancer, including non-small cell squamous cell carcinoma, adenocarcinoma, and large cell carcinoma. "A previous study revealed that Bru directly interacts with S-phase Kinase-Associated Protein 1, impairing the proliferation and metastasis of non-small cell lung cancer." (PMID 40563453, 2025). "Here we showed that Skp1 was overexpressed in 36/64 (56.3%) of non-small cell lung cancers, and elevated Skp1 was associated with poor prognosis." (PMID 26474281, 2015). "In this study, we assessed the expression of Skp1 in non-small cell lung cancers (NSCLCs), and screened for Skp1 inhibitors in a total of 21,008 compounds by structure-based high-throughput virtual screening." (PMID 26474281, 2015).
ovarian carcinoma (3 papers, 2021 to 2024). A malignant neoplasm originating from the surface ovarian epithelium. "Moreover, we recently demonstrated that reduced expression of SKP1, CUL1 and RBX1 prevents Cyclin E1 degradation leading to an increase in abundance that induces CIN and promotes cellular transformation in colorectal and ovarian cancer contexts." (PMID 35008511, 2021).
colorectal cancer (2 papers, 2020 to 2022). A primary or metastatic malignant neoplasm that affects the colon or rectum. "In colorectal cancer, SKP1 is highly expressed and is associated with poor patient prognosis." (PMID 36248799, 2022). "SKP1 is a traditional drug target for cancer therapy, while, whether SKP1 promotes colorectal cancer (CRC) stem cells (CRC-SCs) and the underlying mechanisms have remained elusive." (PMID 33292299, 2020). "In conclusion, our results demonstrated that SKP1 promotes YAP-mediated colorectal cancer stemness via degradation of RASSF1." (PMID 33292299, 2020). "To confirm the necessary role of Hippo/YAP signaling in SKP1 promoting CRC stemness, we depleted YAP in SKP1-overexpressing colorectal cancer cells." (PMID 33292299, 2020). "Taken together, these results demonstrated that SKP1 promotes YAP-mediated colorectal cancer stemness via suppressing RASSF1 at both mRNA and protein levels." (PMID 33292299, 2020).
glioblastoma (2 papers, 2015 to 2021). The most malignant astrocytic tumor (WHO grade IV). "Taken together, our results demonstrate that SKP1 is also a bona fide target of miR-148a in glioblastoma." (PMID 25971746, 2015). "Co-transfecting QKI or SKP1 with miR-148a significantly reduced glioblastoma cell invasiveness and decreased the ability of glioblastoma cells to induce HUVEC tube formation." (PMID 25971746, 2015). "QKI suppresses TGF-β signaling in glioblastoma, and SKP1 is an essential component of the E3 ubiquitin ligase complex ROC1-SCFFbw1a, which induces Smad3 ubiquitination." (PMID 25971746, 2015). "Conversely, copy number gains (gains plus amplifications) for SKP1, CUL1, and RBX1 range from 3% (uterine) to 31% (liver), 12% (cervical) to 80% (glioblastoma), and 1% (prostate) to 22% (head and neck), respectively." (PMID 34445249, 2021). "Collectively, SKP1 copy number losses (shallow and deep deletions) range from 7% to 44% in prostate and ovarian cancers, respectively, while CUL1 and RBX1 losses range from 2% (glioblastoma) to 23% (head and neck) and 10% (prostate) to 80% (ovarian), respectively." (PMID 34445249, 2021). "However, combining QKI-3′UTR or SKP1-3′UTR with miR-148a in the glioblastoma cells had no obvious effect compared with transfecting glioblastoma cells with only miR-148a." (PMID 25971746, 2015).